GRP (gastrin releasing peptide)
Diseases named in the same sentence as GRP in open-access papers (continued):
Sharing a sentence is not in itself a finding about the gene and the disease.
gastric cancer (4 papers, 2022 to 2026). A primary or metastatic malignant neoplasm involving the stomach. "Finally, further in vivo and in vitro experiments are needed to verify the functional roles of the three genes (CD36, SERPINE1, and GRP) in gastric cancer that were used to construct the RCDRI index." (PMID 41000398, 2025). "The newly constructed RCDRI consisted of four Regulated cell death-related genes (CD36, SERPINE1, TRIML2, and GRP) and has been shown to be an effective predictive marker for the survival of gastric cancer patients and was trained with multiple external datasets." (PMID 41000398, 2025). "These molecular characteristics were mainly driven by the eight NRGPI oncogenes (CYTL1, PLCL1, CNTN1, GRP, APOD, GPX3, FCN1, SERPINE1) as validated in the gastric cancer cell lines and clinical samples." (PMID 36389725, 2022). "Second, while SERPINE1 was functionally characterized, the roles of other signature components (e.g., C6, GRP, GCG) in gastric cancer remain unclear and merit further investigation." (PMID 41551463, 2026).
lung diseases (4 papers, 2014 to 2025). "Additional pediatric lung diseases have been associated with altered numbers of GRP-positive PNECs." (PMID 25101250, 2014). "Gastrin-releasing peptide has long been held for its possible role as a target for inflammatory disease, including cardiovascular disease, gastrointestinal disease, pulmonary disease, and of course, its roles in endocrine disorders, namely glucose metabolism." (PMID 37759668, 2023). "Ongoing scientific and clinical investigations promise to further clarify the molecular pathways and clinical relevance of GRP in the pathogenesis of diverse pediatric lung diseases." (PMID 25101250, 2014). "The discussion will then summarize the highlights of over 25 years of work from my laboratory regarding the role of GRP in lung development and postnatal lung diseases, especially bronchopulmonary dysplasia (BPD)." (PMID 25101250, 2014). "PNEC abnormalities have been described in seemingly unrelated lung diseases, especially PNEC hyperplasia or elevated GRP levels in association with inflammatory lung diseases, a few of which will be briefly discussed here." (PMID 25101250, 2014). "Intercohortal comparison as a function of the underlying pulmonary disease entity evidenced no substantial differences in GRP concentrations." (PMID 37020080, 2023).
small cell carcinoma (4 papers, 2014 to 2024). A neuroendocrine carcinoma composed of small malignant cells which are often said to resemble "oat cells" under the microscope. "Serum levels of neuron-specific enolase (NSE) and pro-gastrin-releasing peptide (pro-GRP), tumor markers of small-cell carcinoma, were also elevated [NSE, 25.8 ng/ml, (normal range, 0–12 ng/ml); pro-GRP, 152.0 pg/ml (normal range, <80.0 pg/ml)]." (PMID 24944702, 2014).
Brain tumor (3 papers, 2002 to 2018). "Some brain tumours, such as glioblastomas express high levels of receptors for bombesin/gastrin releasing peptide." (PMID 11953892, 2002). "It has been shown that a high percentage of brain tumour cell lines, including U-87MG, express receptors for BN/GRP." (PMID 11953892, 2002). "Brain tumor tissue studied by Western blot and immunohistochemistry (IHC) showed a marked increase in the constitutive expression of Hsp27, Hsp90, GRP (glucose regulated proteins) 78 and 75, and Hsc70 (or Hsp70) and the co-chaperone HspBP1 (Hsp70 Binding Protein 1)." (PMID 30189598, 2018). "In addition, some alterations in GRP or GRPR expression or function have been described in patients with neurodegenerative, neurodevelopmental, and psychiatric disorders, as well as in brain tumors." (PMID 23251133, 2012).
chronic kidney disease (3 papers, 2020 to 2022). Impairment of the renal function secondary to chronic kidney damage persisting for three or more months. "In the present study, we investigated the effect of GRP inhibition on phosphate-induced calcification in VSMCs in vitro, an arterial ring ex vivo and the aorta of chronic kidney disease (CKD) mice in vivo and elucidated the underlying mechanism." (PMID 32192106, 2020).
glioblastoma (3 papers, 2002 to 2024). The most malignant astrocytic tumor (WHO grade IV). "In the human glioblastoma cell line U-138-MG, GRP stimulated proliferation only when combined with agents that increase cellular cAMP (forskolin, 8-Br-cAMP, PDE inhibitor), but proliferation was not seen when either agent was present alone." (PMID 34539578, 2021). "In the human glioblastoma cell line U-138-MG, GRP stimulated proliferation when combined with agents that increase cellular cAMP (forskolin, 8-Br-cAMP, PDE inhibitor), but not when either was present alone." (PMID 34539578, 2021). "In the human glioblastoma cell line U-373MG, Bn peptides (GRP, NMB) stimulate DNA synthesis, which is mediated by GRPR." (PMID 34539578, 2021). "GRP has also been used for the delivery of irinotecan, a chemotherapeutic drug, to treat glioblastoma in in vitro and in vivo studies, showing an anticancer effect against U-87MG glioblastoma cells." (PMID 39063232, 2024). "In view of findings that 85% of human glioblastoma cell lines express functional receptors for BN/GRP, we evaluated in this study the efficacy of targeted chemotherapy based on cytotoxic analogue of BN, AN-215 in U-87MG human glioblastoma xenografted into nude mice." (PMID 11953892, 2002). "Thus, the treatment with AN-215 did not affect the binding characteristics of receptors for BN/GRP in U-87MG human glioblastoma." (PMID 11953892, 2002).
glioma (3 papers, 2012 to 2024). A benign or malignant brain and spinal cord tumor that arises from glial cells (astrocytes, oligodendrocytes, ependymal cells). "GRPR activation by GRP or bombesin stimulates the growth of glioma cell lines." (PMID 23251133, 2012). "The following peptides, through their respective receptors, promote glioma progression (proliferation, migration, invasion, and angiogenesis): AMD, angiotensin II, GRP, bradykinin, CCK, endothelin, neuromedin B, neurotensin, and substance P." (PMID 39063232, 2024). "High DEGs in grade II gliomas included NNMT, MFAP5, APCDD1L-AS1, C7orf57, HP, SERPINA5, and LTF and some highly downregulated DEGs included ABCA4, PDE6A, GRP, RD3, and TMEM72." (PMID 33948562, 2021).
melanoma (3 papers, 2010 to 2025). A malignant, usually aggressive tumor composed of atypical, neoplastic melanocytes. "RNA-seq analysis of GRP-stimulated human and murine melanoma lines indicated the activation of key cancer-related pathways, notably anoikis resistance and invasion." (PMID 40500450, 2025). "We used PamGene kinase assays to identify the main pathway activated by GRP/GRPR in melanoma cells." (PMID 40500450, 2025). "Inhibiting β-catenin (iCRT3 and siCtnnb1) reduced GRP-induced invasion in mouse melanoma." (PMID 40500450, 2025). "However, elevated levels of GRP have been highlighted in nodular melanomas and melanomas with increased amounts of melanin." (PMID 34068618, 2021). "By contrast, in other carcinomas or melanoma, GRPR is probably activated at metastatic sites by locally produced GRP." (PMID 40500450, 2025). "Early studies have shown that A375-6 melanoma cell line growth is not hindered by bombesin, the GRP amphibian homolog, nor by GRP receptor antagonists." (PMID 34068618, 2021).
neuroendocrine carcinoma (3 papers, 2017 to 2024). A malignant neuroendocrine neoplasm composed of cells containing secretory granules that stain positive for NSE and chromogranin. "Elevated serum tumor markers NSE and Pro-GRP are commonly associated with poorly differentiated neuroendocrine carcinomas (NECs)." (PMID 39061142, 2024). "Although there was no report of preoperative prognostic serum tumor marker of high-grade neuroendocrine carcinoma, from the result of our study, preoperative Pro-GRP could be the prognostic factor after operation." (PMID 29454358, 2018).
Obesity (3 papers, 2019 to 2023). Accumulation of substantial excess body fat. "In addition, a number of other risk factors are shared in the development of OA and bladder cancer, such as obesity and metabolic syndrome, coffee consumption, higher serum IGF‐1 concentration, Brazilin, Chondromodulin‐1,59 vitamin K‐dependent protein, and GRP/Ucma." (PMID 38100139, 2023). "GRP is a regulatory neuropeptide that stimulates gastric G cells to release gastrin and regulate gastric acid secretion and intestinal movement, which affects the food intake and may lead to anorexia, bulimia, and obesity if lacked of the genes." (PMID 31024621, 2019).
renal cell carcinoma (3 papers, 2018 to 2024). "As a receptor for gastrin-releasing peptide (GRP), GRPR promotes renal cell carcinoma by activating ERK1/2 pathway together with GRP." (PMID 30466390, 2018).
Allergy (2 papers, 2017 to 2025). An allergy is an immune response or reaction to substances that are usually not harmful. "In conclusion, our results indicated that GRP is a cross‐reactive allergen between JA and peaches, and might be a causative allergen of JA allergy, especially FDEIA." (PMID 28685994, 2017). "We identified GRP as the first allergen in JA allergy and investigated cross‐reactivity between JA GRP and Pru p 7 in JA allergy." (PMID 28685994, 2017). "The mean percentage of basophil CD203c expression induced by JA GRP at the highest concentration, 1 ng/mL, was 48.7% (39.7–91.3%) and 4.1% (3.4–4.9%) in JA allergy patients and four non‐JA allergic subjects, respectively." (PMID 28685994, 2017). "Cross‐reactivity between JA GRP and Pru p 7 support the co‐existence of allergy to both JAs and peaches in our JA patients." (PMID 28685994, 2017). "We identified GRP as the first allergen, Pru m 7, in JA allergy." (PMID 28685994, 2017). "Because GRP allergies are likely to be severe systemic reactions, BAT might be a useful diagnostic tool for screening GRP allergies to reduce the requirement for oral food challenges and to make correct diagnoses." (PMID 28685994, 2017). "In addition, ELISA inhibition assays using sera from JA allergy patients indicated cross‐reactivity between JA GRP and Pru p 7, suggesting that patients sensitized by GRP from JA might have cross‐reactivity to peaches and vice versa." (PMID 28685994, 2017). "However, further investigation of a large number of subjects is required to clarify whether GRP sensitization might be involved in JA allergy provoked by cofactors." (PMID 28685994, 2017).
Anxiety (2 papers, 2023 to 2025). Intense feelings of nervousness, tension, or panic often arise in response to interpersonal stresses. "Abnormal expression of brain-gut peptides, like ghrelin, NPY, CCK, PYY, and GRP, in the peripheral and central systems can lead to depression, anxiety, gastrointestinal diseases, and metabolic disorders." (PMID 37511879, 2023).
atherosclerosis (2 papers, 2018 to 2020). A disease characterized by the build-up of fatty material and calcium deposition in the arterial wall resulting in partial or complete occlusion of the arterial lumen. "Increasing evidence has suggested that GRP and its receptor signaling promote endothelial dysfunction and migration and proliferation of VSMCs, which leads to the development of atherosclerosis." (PMID 32192106, 2020). "We previously reported that GRP induces endothelial dysfunction and the proliferation/migration of vascular smooth muscle cells, the main events of the progression of atherosclerosis." (PMID 30544709, 2018).
breast tumors (2 papers, 2018 to 2019). "Moreover, GRP elicits mitogenic effects in a number of cancerous tissues including breast tumors." (PMID 30513833, 2018). "Among the many peptide receptor systems, gastrin-releasing-peptide (GRP) receptors, the mammalian equivalent of bombesin (BN) receptors, are potential targets for diagnosis and therapy of breast tumors due to their overexpression in various frequently occurring human cancers." (PMID 30887136, 2019).
bronchopulmonary dysplasia (2 papers, 2014 to 2024). Bronchopulmonary dysplasia is a chronic respiratory disease that results from complications related to lung injury during the treatment of infant acute respiratory distress syndrome in low-birth-weight premature infants or from abnormal lung development in older infants. "In a baboon model of bronchopulmonary dysplasia, some of the lung defects associated with the disease could be prevented by treatment of the animals with a GRP-blocking antibody, directly linking PNEC-secreted GRP to the disease phenotype." (PMID 38813849, 2024).
bulimia (2 papers, 2012 to 2019). "One study found significantly reduced GRP levels in the CSF of women who were recovered from bulimia nervosa, compared to women recovered from anorexia or healthy control women." (PMID 23251133, 2012). "The authors suggested that persistent alterations in GRP levels after recovery indicate that this alteration might be trait-related and contribute to episodic hyperphagia in patients with bulimia nervosa." (PMID 23251133, 2012).
chronic lung disease (2 papers, 2014 to 2023). According to the definitions of the American and British Thoracic Societies, including pulmonary functional tests, X-rays, and CT scans for items such as fibrosis, bronchiectasis, bullae, emphysema, nodular or lymphomatous abnormalities. "Early and excessive GRP secretion is associated with chronic lung disease in infants." (PMID 25101250, 2014). "The focus of this collaborative work has now intensified: to determine how transient, early GRP elevation triggers chronic lung disease with fibrosis weeks to months later." (PMID 25101250, 2014). "Analysis of GRP+ PNECs or urine GRP levels in patients post-RT could clarify the disease pathogenesis and potentially set the stage for GRP-blockade treatment to prevent the chronic lung disease in similar clinical settings." (PMID 25101250, 2014).
erectile dysfunction (2 papers, 2009 to 2025). Persistent or recurrent inability to achieve or to maintain an erection during sexual activity. "Dysfunction of the GRP and SNB systems, whether resulting from spinal cord injury, peripheral neuropathy, or hormonal deficiencies, can lead to erectile dysfunction or failure of ejaculation, which in turn may indirectly prevent fertilization." (PMID 41008302, 2025). "We conclude that the spinal GRP system appears to be a stress-vulnerable center for male reproductive functions, which may provide new insight into a clinical target for the treatment of erectile dysfunction triggered by stress and psychiatric disorders." (PMID 19169356, 2009).
head and neck cancer (2 papers, 2011 to 2025). A primary or metastatic malignant neoplasm affecting the head and neck. "Adding GRP to head and neck cancer cells HNSCC causes Src-dependent cleavage of EGFR ligands." (PMID 41007372, 2025). "Adding gastrin-releasing peptide (GRP) to head and neck cancer cells increases the tyrosine phosphorylation of the EGFR within minutes in a Src-dependent mechanism." (PMID 41007372, 2025). "Intriguingly, Grandis and colleagues have demonstrated that Gastrin releasing peptide (GRP)/GRP receptor autocrine pathway can transactivate EGFR head and neck cancer cell lines." (PMID 21423656, 2011).
Insulin resistance (2 papers, 2022 to 2024). Increased resistance towards insulin, that is, diminished effectiveness of insulin in reducing blood glucose levels. "The decline of GRP chaperone proteins level is related with metabolic disorders, and upregulation of GRP chaperone proteins improve insulin resistance in the diabetic prone mice." (PMID 36564376, 2022).
migraine (2 papers, 2022 to 2023). "Since GRP has been linked to migraine and other headache disorders, hypoxia could be regarded as initiator for headaches on a neurotransmitter basis." (PMID 36148300, 2022). "Finally, the associations of migraines with circadian or circannual rhythm-related neuropeptides other than PACAP, such as VIP, GRP, AVP, NMS, and DA, were described." (PMID 37373239, 2023). "GRP, AVP, GABA, and NMS have been poorly studied in migraine patients." (PMID 37373239, 2023).
oral cancer (2 papers, 2023 to 2025). "Additionally, treatment with neutralizing monoclonal antibodies against GRP effectively inhibited the growth of oral cancer cells, demonstrating inhibitory effects both in vivo and in vitro." (PMID 41266536, 2025). "It has been reported that ligands of GPCRs, such as prostaglandin (PGE2) and gastrin-releasing peptide (GRP), which are often overexpressed in oral cancer, can activate GPCR and Src-mediated matrix metalloproteinase (MMP), leading to the cleavage and release of EGFR ligands." (PMID 38004424, 2023).
panic attacks (2 papers, 2012 to 2025). "More recently, however, the possibility that GRP and GRPR are candidate genes in panic disorders was not confirmed in an association and linkage analysis." (PMID 23251133, 2012).
allergic conjunctivitis (1 paper, 2023). "In the present study, we analyzed the involvement of GRP/GRPR in the transmission of acute itchy eyes and did not analyze the effect of GRP/GRPR on pain in the trigeminal system or in pathological models of allergic conjunctivitis." (PMID 38098939, 2023).
asthma (1 paper, 2021). "GRP receptor blockade may serve as a broad spectrum of anti-inflammatory therapy for asthma, since reduced neutrophilic inflammation and cytokine production triggered by ozone were reduced with GRP blocking agent or antibody." (PMID 34948451, 2021).
atopic dermatitis (1 paper, 2020). "A previous study using an atopic dermatitis murine model (NC/Nga mice) revealed that LCN2 produced by activated astrocytes in the spinal cord enhanced itch induced by GRP, an itch-specific neuropeptide." (PMID 33182442, 2020).
calcification (1 paper, 2020). Process by which organic tissue becomes hardened by the physiologic deposit of calcium salts. "Here, we found that the increased expression of GRP and GRP receptor was involved in HP-induced vascular calcification in CKD mice and RC-3095 treatment significantly attenuated the arterial medial calcification in them, making GRP a potential therapeutic target for vascular calcification in CKD." (PMID 32192106, 2020).
chronic heart failure (1 paper, 2022). "Out of the gastric peptides studied, secretin and gastrin-releasing peptide were significantly lower in patients with chronic heart failure than in controls." (PMID 34806426, 2022).
ciliopathy (1 paper, 2019). A genetic disorder of the cellular cilia or the cilia anchoring structures, the basal bodies, or of ciliary function. "The observed liver involvement with elevated GOT/GRP is also a typical finding of this ciliopathy." (PMID 30858804, 2019).
colitis (1 paper, 2023). Inflammation of the colon. "A previous report indicated that the blockade of receptor channels such as TRPV1 and TRPA1 on nociceptive sensory neurons was shown to attenuate experimental colitis by suppressing the release of GRP and SP." (PMID 36910013, 2023).
contact dermatitis (1 paper, 2020). An inflammatory skin condition caused by direct contact between the skin and either an irritating substance or an allergen. "Similar to contact dermatitis as previously reported, 6 upregulation of GRP and GRPR directly indicates the enhancement of the GRP‐GRPR system under psoriatic itch." (PMID 32584520, 2020).
cystic fibrosis (1 paper, 2014). Autosomal recessive disorder caused by pathogenic variants in the CFTR gene (cystic fibrosis transmembrane conductance regulator), which encodes a chloride and bicarbonate channel expressed in epithelial cells, and follow the diagnosis criteria. "Cystic fibrosis has also been associated with increased numbers of PNECs immunostaining for GRP, calcitonin, and serotonin." (PMID 25101250, 2014). "Elevated GRP has been associated with oxidative stress in humans including cystic fibrosis patients, asymptomatic smokers, and patients with chronic obstructive pulmonary disease." (PMID 25101250, 2014).